ENSG00000285085 (novel protein)
Gene: Protein-coding gene on chromosome 6 (32,150,495 to 32,154,373, reverse strand). Ensembl gene ENSG00000285085.
Genetic constraint (gnomAD): Loss-of-function variants: 3 observed, 3.1 expected, observed/expected ratio (o/e) 0.97, 90% interval 0.42 to 1.85. That is too few expected variants to judge how well the gene tolerates losing a copy. Missense variants: 74 observed, 58.6 expected, observed/expected ratio (o/e) 1.26, 90% interval 1.05 to 1.53. Synonymous variants: 40 observed, 29.05 expected, observed/expected ratio (o/e) 1.38, 90% interval 1.07 to 1.77.